CXCR2 (C-X-C motif chemokine receptor 2)
Diseases named in the same sentence as CXCR2 in open-access papers (continued):
Sharing a sentence is not in itself a finding about the gene and the disease.
breast cancer (continued). "Furthermore, CXCR2 antagonist SB225002 combined with DTX in vivo not only dramatically inhibited the tumor growth but also significantly decreased stemness of breast cancer cells, suggesting CXCR2 may be a potential therapeutic target for breast cancer patients with high expression of CCL20." (PMID 36859354, 2023). "In this study, patients with HER2-negative breast cancer received reparixin, a CXCR1/CXCR2 antagonist, prior to surgical tumor removal." (PMID 37108425, 2023). "Activation of several Gi/o-coupled chemokine receptors, including CCR2, CXCR1, and CXCR2, by their cognate ligands was found to stimulate CSC activity in HER2+ breast cancer." (PMID 35406489, 2022). "In breast cancer, CXCL1 can elicit cancer progression and immune escape programs, and targeting the CXCL1/CXCR2 axis can improve treatment." (PMID 35468838, 2022). "The Serpine2-Pleur axis was also involved in the communication of lymphatic ECs with Cxcr2+Ly6g- granulocytes, alv macrophages and classical monocytes in the lung PMN of breast cancer." (PMID 36612175, 2022). "The CXCL8/CXCR2 axis plays important roles in the initiation and development of various cancers including CRC, breast cancer, prostate cancer, and lung cancer." (PMID 35898871, 2022). "CXCR2 and CXCL8 regulate breast cancer progression in the TME by modulating several related pathological processes, including promoting breast cancer growth, angiogenesis, invasion, metastasis, and reducing cancer cell sensitivity to chemotherapy." (PMID 33747948, 2021). "Like CXCR2, CXCR1 is expressed significantly in breast cancer stem cells, which increases the growth of breast cancer when stimulated by inflammation or tissue damage." (PMID 33747948, 2021). "Taken together, these data show that compared to ER+ breast cancer cells, TNBC cells overexpress a number of potential neutrophil recruiting factors, the most abundant of which being the CXCR2 specific GRO chemokines and TGF-β1." (PMID 33912188, 2021). "We have shown recently that CXCR2 was mainly expressed by neutrophils in breast tumors and was present at higher levels in TNBC compared to luminal or Her2-positive breast cancers." (PMID 34066060, 2021). "CXCR2 is considered a novel CSC marker for only TNBC and is also involved in breast cancer angiogenesis and metastasis, treatment resistance, and recurrence." (PMID 33805447, 2021). "As the CXCL1/CXCR2 axis is required for lung metastasis in breast cancer, we therefore analyzed levels of CXCL1/CXCR2 expression in lung specimens." (PMID 32079335, 2020). "We have previously shown that the ligands of human chemokine receptor CXCR2 (CXCL1, CXCl2, CXCL3, CXCL5, CXCL6, CXCL7 and CXCL8) were coregulated in breast cancers, presumably because of their common location in a narrow region of chromosome 4q." (PMID 32727083, 2020). "It is also interesting to note that CXCR4, another chemokine receptor, shows a higher expression in breast cancer tissue, whereas its ligand CXCL12 is downregulated in the same tissue, which is in contrast to the situation observed for CXCR2." (PMID 32727083, 2020). "In breast cancer, the SDF-1/CXCR4 and CXCL5/CXCR2 axes recruit Gr-1+CD11b+ myeloid cells, activate MMP, and upregulate TGF-β1, which contributes to metastasis in mouse models injected with a breast cancer cell line (4T1)." (PMID 32726950, 2020). "Examples of this include, the bioactive lipid, lysophosphatidic acid, and its receptor, LPAR-1 in breast cancer, chemokines, CXCL8/IL8 and CXCR1 and CXCR2 in melanoma, pancreatic cancer and gastric tumors and CXCL12 and CXCR4 in multiple cancers." (PMID 33329395, 2020). "Increased CXCR2 and its ligands CXCL1, CXCL5, and CXCL7 were found in co-cultured MSCs and breast cancer, with this axis augmenting breast cancer cell migration." (PMID 31130595, 2019). "CXCL8, a ligand for CXCR2, has been shown to regulate osteoclast activation both in a RANKL dependent and independent pathway during breast cancer bone metastasis." (PMID 30871004, 2019).
breast cancer (continued). "Another ligand, CXCL8, which binds to CXCR2 has been shown to influence bone metastasis in a RANKL-dependent and independent manner in breast cancer." (PMID 30871004, 2019). "We stained human femoral head tissue sections from a patient with breast cancer metastasis to bone for CXCL5 and CXCR2 by IHC." (PMID 31562303, 2019). "The Interleukin 8 (IL-8) gene and its receptor, CXCR2, have been described as markers of tumor progression, acting through repression of the AKT1 gene on breast cancer cell lines." (PMID 30173296, 2018). "Here, we confirmed that Ly6GmiLy6CloCD11b+CXCR2+ MDSC subsets (CXCR2+ MDSCs) were the main subpopulation of MDSCs expanding and recruiting during breast cancer progression." (PMID 29383101, 2017). "We have previously shown that human epithelial breast cancer cells undergoing an EMT via overexpression of brachyury markedly upregulate the expression of IL-8 and its receptors, CXCR1 and CXCR2." (PMID 27248176, 2016). "CXCR2 and its ligand CXCL1 contribute to the resistance of chemotherapy in mammary tumor cells and the knockdown of CXCR2 enhances sensitivity to chemotherapy and inhibits tumor cell metastasis." (PMID 26313265, 2015). "Lymphangiogenesis in human breast cancer samples can be correlated with clinical parameters and CXCL7/CXCR2 staining." (PMID 20652010, 2010). "Despite studies on increased expression of CXCR2 in breast cancer, reports on CXCL7 in breast cancer are limited." (PMID 20652010, 2010). "Our results indicated that the polymorphisms in IL-8 and CXCR2 genes are associated with increased breast cancer risk, as well as disease progress, supporting our hypothesis for IL-8 and ELR+CXC chemokine receptor (CXCR2) involvement in breast cancer pathogenesis." (PMID 20540789, 2010). "Therefore, we verified the effect of IL-8 on the growth of breast cancer cells using breast cancer cell lines with CXCR1 knockdown and CXCR2 knockdown." (PMID 40839237, 2025). "Similarly, in breast tissue, estrogen promotes neutrophil recruitment through the CXCR2 pathway and enhances N2 polarization by upregulating LFA-1 expression, ultimately driving breast cancer metastasis." (PMID 40739091, 2025). "Hence, targeting CXCL1/CXCR2 signaling has emerged as a pivotal strategy for improving the prognosis of breast cancer, with potential benefits for patients resistant to chemotherapy through the use of CXCL1/CXCR2 antagonists." (PMID 39394189, 2024). "CXCL3 binds to CXCR2, a receptor on breast cancer cells, and activates FAK, which promotes a mesenchymal phenotype, invasion, and metastasis of breast cancer cells F12 expression might affect the OS of PTC patients by regulating metabolic pathways." (PMID 39497824, 2024). "Blocking the recruitment of MDSCs to the tumor microenvironment has been attempted using chemokine inhibitors that target pathways such as CCR5 (Maraviroc) and CXCR2 (Reparixin) in phase 1/2 clinical trials for metastatic colorectal cancer (NCT 01736813) and breast cancer (NCT 02370238)." (PMID 39513886, 2024). "Interestingly, the mRNA expression of the IL-17/CXCR2 axis players CXCR2, IL17 and IL17R increased in Cl66, a doxorubicin- and paclitaxel-resistant murine breast cancer cell line." (PMID 37566060, 2023). "Therefore, this study reveals the potential of blocking CXCR2 activation or CCL2 signaling pathway in inhibiting tumor growth and paclitaxel resistance in breast cancer." (PMID 37821959, 2023). "Inhibiting CXCR2 might trigger ferroptosis in breast cancer cells, suggesting a potential role of the CXCL8-CXCR2 axis in ferroptosis." (PMID 37765018, 2023). "Moreover, CXCR2 knockout and CXCR2−/−MDSCs transplantation significantly impaired CUMS-mediated MDSC elevation, PMN formation, and breast cancer metastasis." (PMID 37210553, 2023).
breast cancer (continued). "Importantly, we found that breast cancer-derived CXCL1-3 and CXCL8 bind to the receptor CXCR2 and activate the ERK1/2 signaling pathway to initiate the expression of LIF by activating transcription factors NF-κB and Stat3 in CAAs in paracrine manner." (PMID 35280694, 2022). "In addition, we detected the mRNA levels of CXCL1-3 and CXCL8 in cancer tissues, and CXCR2 and LIF in adipocytes adjacent to breast cancer of clinical breast cancer specimens." (PMID 35280694, 2022). "Importantly, the role of CAA in promoting breast cancer progression has been confirmed in vivo, and the combined targeting of LIF and CXCR2 can significantly reduce breast cancer metastasis." (PMID 35280694, 2022). "The IL-8/CXCR2/WNT feedback loop was also observed in the development of chemoresistance and metastasis in estrogen receptor (ER)-positive breast cancer, in which WNT signaling is specifically mediated by WNT3A coupled with SNAI1/nuclear factor (NF)-κB signaling activation." (PMID 34799554, 2021). "Using a cohort of breast cancer patients for which we had obtained data on multiple cytokines, including CXCL8 as well as immune infiltration, we have first performed an extensive review of available CXCR2 Ab, as CXCR2 immunostaining remains controversial." (PMID 32727083, 2020). "Breast cancer patients treated with chemotherapeutic drugs exhibited poor survival rate (66.7 vs 282.8 months, P=0.00071) and shorter disease-free survival time if their tumor samples expressed high level of IL8, CXCR1, CXCR2 genes and Wnt target genes." (PMID 28703802, 2017). "In the primary tumors developed by 4T1 mouse breast cancer cells, inhibition of either CCR2 or CXCR2 can reduce the number of macrophages, which also suggests the involvement of multiple chemokine signals in the macrophage accumulation in the tumor microenvironment." (PMID 26275794, 2015). "Depletion of IL-8 in mammary carcinoma cells with forced expression of TFF3, or antibody inhibition of IL-8, partially abrogated mammary carcinoma cell TFF3-stimulated HUVEC angiogenic behavior in vitro, as did inhibition of the IL-8 receptor, CXCR2." (PMID 26559818, 2015). "In breast cancer cells, hPTTG1 overexpression reinforces OIS through a CXCR2/p21 signaling." (PMID 22789011, 2012). "Additionally, CXCR2 and CXCR4 can recruit Gr-1+CD11b+ myeloid cells into invasive front of mammary tumor, an event that directly promotes tumor metastasis." (PMID 20419088, 2010). "The reason may be that CXCR2 activation can be affected by not only IL-8 signaling but also CXCL1 signaling, indicating that CXCR2 is the key target through which depression promotes the progression of breast cancer." (PMID 40839237, 2025). "We sequentially evaluated the protein expression of CXCR2 in ALDH+ BCSCs and found that CXCR2 protein was highly expressed in ALDH+ BCSCs by western blotting, suggesting that CXCR2 might play a critical role in activating the stemness of breast cancer." (PMID 36859354, 2023). "CXCR2 antagonist SB225002 combined with DTX may be a hopeful therapeutic strategy to overcome chemoresistance and gain better clinical outcomes in patients with breast cancer, especially CCL20high-expressing breast cancer." (PMID 36859354, 2023). "Furthermore, we verified that adipocytes enhanced lung metastasis of breast cancer cells, and the combination of EC330 (targeting LIF) and SB225002 (targeting C-X-C motility chemokine receptor 2 (CXCR2)) significantly reduced lung metastasis of breast cancer cells in vivo." (PMID 35280694, 2022). "All this suggests that high expression of CXCR2 could favor a better outcome of TNBCs, which is also in agreement with our previous results obtained for all types of breast cancers, not just TNBCs." (PMID 34066060, 2021). "Overall, the discrepancy observed for the prognosis value of CXCR2 in breast cancer might be related to the lack of specificity of the Ab used." (PMID 32727083, 2020).
breast cancer (continued). "However, counteracting neutrophil trafficking (by NLRP3 inhibition) or neutrophil aging (by CXCR2 blockade) attenuated tumor progression, whereas supporting neutrophil aging (by blockade of CXCR4) even enhanced tumor growth in SCC VII HNSCC and 4T1 breast cancer." (PMID 34876407, 2021). "In keeping, breast cancer CSC were shown to proliferate in vitro in response to the addition of exogenous CXCL8 while a small molecular weight antagonist of CXCR1/2 (reparixin) or a blocking anti-CXCR1 (but not anti-CXCR2) monoclonal antibody were both able to deplete CSC in vitro." (PMID 30788286, 2019). "Finally, various orally active small-molecule non-competitive antagonists of CXCR1 and CXCR2, such as SCH527123 (Merck), repertaxin (Dompé, Milan, Italy), and SCH479833 (Merck, Whitehouse Station, NJ, USA), have demonstrated anti-tumor effects in breast cancer xenograft models." (PMID 36835413, 2023).
pancreatic cancer (110 papers, 2010 to 2026). "CXCR2 deficiency reduces pancreatic cancer vascular density, while blocking CXCR2-CXCL8 enhances PD-1 efficacy." (PMID 40443678, 2025). "CXCR2 overexpression in human lung cancer tissue has been linked to a poor prognosis, while CXCR2 agonists have been proposed as potential diagnostic biomarkers in pancreatic cancer patients." (PMID 36555469, 2022). "The loss or inhibition of CXCR2 enables the entry of T cells into the pancreatic cancer TME and enhances the antitumor immune function of the TME." (PMID 36324574, 2022). "CXCR2 signaling is upregulated much more in neutrophil/MDSCs than in human pancreatic cancer cells and is associated with poor prognosis in patients." (PMID 35011369, 2021). "C-X-C motif chemokine receptor 2 (CXCR2) controls a major inflammatory signaling network in pancreatic cancers with KRAS mutation." (PMID 34638560, 2021). "The role of the triad of neutrophils, MDSCs, and CXCR2 has been implicated in pancreatic tumors, and an elevated neutrophil count showed poor outcome in patients with pancreatic tumors." (PMID 29662489, 2018). "CXCR2 has been associated with to the biological behavior of tumors in colon cancer, oral squamous cell carcinoma, pancreatic cancer, and hepatocellular carcinoma." (PMID 29312644, 2017). "Therefore, larger samples are needed to further evaluate the association between CXCR2 expression and the prognosis of patients with pancreatic cancer." (PMID 29312644, 2017). "As CXCR2 expression was upregulated downstream of CPE-ΔN in the HCC cells, we speculated whether CXCR2, a chemokine receptor implicated in driving pancreatic cancer metastasis could be regulated by CPE-ΔN in Panc-1 cells as a mechanism to promote the proliferation and invasion of these cells." (PMID 31731578, 2019). "A previous study has found that the CXCL8/CXC chemokine receptor 2 (CXCR2) axis participates in mediating the transport and infiltration of M2 macrophages in pancreatic cancer." (PMID 41293091, 2025). "In the context of pancreatic cancer (PC), macrophages with a CXCR2 phenotype display immunosuppression due to M2 polarization." (PMID 40959082, 2025). "Elevated expression of CXCR2 and its ligands consistently correlated with poor survival in pancreatic cancer patients." (PMID 41228334, 2025). "Our findings indicate a variation in the expression of CXCL5 and CXCR2 between primary foci and metastases in pancreatic cancer." (PMID 38430267, 2024). "Instead, CXCL1 played a role in promoting angiogenesis in a paracrine manner in human vascular endothelial cells (HUVECs), and blocking CXCR2 in an orthotopic murine pancreatic cancer model reduced the tumor volume and inhibited the microvessel density." (PMID 38339310, 2024). "This corroborates the finding of previous in vivo studies that CXCR2 inhibition can reduce neutrophil mobilization and recruitment to pancreatic tumor tissue in mouse models." (PMID 38898176, 2024). "In this work, we engineered a human cell-based NTI-chip that enabled us to decipher the tumor-promoting mechanisms of neutrophils and the tumor-suppressive mechanisms of CXCR2 inhibition as a novel neutrophil-based immunotherapy in pancreatic cancer." (PMID 38898176, 2024). "Therapeutic strategies to target the CXCR-1/CXCR-2 axis or combination with immunotherapy have been proposed to improve antitumor efficacy in pancreatic cancer, metastatic melanoma, and metastatic colorectal carcinoma." (PMID 38358826, 2024). "NHERF1-mediated functional coupling of CXCR2 and PLC-β3 will form a macromolecular complex, which is essential for CXCR2 signal transduction and malignant progression of pancreatic cancer." (PMID 37576896, 2023).